IL1B (interleukin 1 beta)
Diseases named in the same sentence as IL1B in open-access papers (continued):
Sharing a sentence is not in itself a finding about the gene and the disease.
pulmonary fibrosis (continued). "More recently, a study showed that bleomycin and IL-1β-mediated pulmonary fibrosis was IL-17A dependent." (PMID 21858022, 2011). "Inhibition of IL-1β prevented the fibrotic reaction induced by bleomycin in mice, while its transient expression induces lung injury and pulmonary fibrosis in the late stages of the experimental setting." (PMID 17118201, 2006). "We chose to test cytokines and factors known for their different activities on the development of lung fibrosis: proinflammatory (IL-1β and TNF-α), profibrotic (IL-4 and TGF-β) and antifibrotic mediators (IL-9 and PGE-2)." (PMID 16045809, 2005). "Subsequent correlation analysis indicated that Lactobacillus was significantly positively associated with physiological data, including serum IL‐1β, TNF‐α, TGF‐β, and indexes related to pulmonary fibrosis, and Muribaculaceae was obviously negatively associated with physiological data." (PMID 41509197, 2026). "Oroxylin A reduced inflammatory score and bronchiolar epithelium thickness, inhibited airway construction and central airway resistance, improved pulmonary fibrosis, increased inspiratory capacity and quasi‐static compliance, and suppressed IL‐1β and IL‐6 activity levels in mice model of RP." (PMID 41509128, 2026). "Potential Mechanisms: 1) Plasma cell-derived cytokine production: Malignant plasma cells in MM produce multiple cytokines (IL-6, TNF-α, IL-1β) that may trigger pulmonary fibrosis through Th2-mediated immune responses." (PMID 41477374, 2025). "IL-1β further promotes the transformation of fibroblasts and may in turn increase the production of ROS, leading to the continuous progression of pulmonary fibrosis." (PMID 40391214, 2025). "Notably, inhibiting NLRP3 or IL-1β signaling has been shown to slow disease progression and reduce the severity of lung fibrosis by reducing collagen deposition and TGFβ activity." (PMID 40119408, 2025). "Besides its own profibrotic action, TGF-β1 activates the synthesis of other pro-inflammatory cytokines that are involved in the development of pulmonary fibrosis, such as IL-1β and TNF-α." (PMID 41597294, 2025). "Given IL-1β’s role in promoting lung fibrosis, we asked whether activated alveolar macrophages could secrete IL-1β in vitro." (PMID 40887574, 2025). "However, treatment with saroglitazar or BrMSCs initiated 14 days after pulmonary fibrosis induction significantly (p < 0.05) reduced the IL-1β concentration and increased IL-10 levels compared to their levels in BLM-G." (PMID 38376539, 2024). "In addition, a study confirms that inhibition of ERK1/2 attenuates bleomycin-induced pulmonary fibrosis, in which IL-1β plays a key role, by inhibiting the EMT induction." (PMID 39118068, 2024). "The pro-inflammatory cytokines IL-1β and IL-18 were elevated in PBMCs of IPF patients and mice with BLM-induced pulmonary fibrosis, with this increase linked to the release of the pro-fibrotic cytokine TGF-β through an AIM2 canonical inflammasome-dependent pathway." (PMID 39795884, 2024). "Similarly, skin and lung fibrosis worsened in wild-type mice following the transplantation of leukocytes with high expression of IL-1β and TNF-α." (PMID 39866843, 2024). "Taking into account that IL1β has been shown to play a role in lung injury and pulmonary fibrosis, detection of NC in VMT-positive cells (including FLCs) indicates the involvement of VMT not only in the viral life cycle but also the pathogenesis induced by SARS-CoV-2 infection." (PMID 36842152, 2023). "During Spn infection, glucose transporter 1-dependent glycolysis in macrophages could activate caspase-1 and triggered the production of proinflammatory cytokines such as IL-1β and IL-18, thereby promoting the exacerbation of lung fibrosis in mice." (PMID 38007420, 2023).
pulmonary fibrosis (continued). "Afterward, we used Metascape for the pathway enrichment analysis of this network, and we found that the most significant terms within the cluster consisting of EGF, IL-1β, IL-3, TNF-α, CCL2 were associated with lung fibrosis and proinflammatory/fibrotic mediators." (PMID 36733673, 2023). "RGC32 deficiency in mice impairs the polarization of classically activated macrophages, attenuates the expression of inflammatory mediators in macrophages, including the fibrosis inducers iNOS and IL-1β, which are regulated by NFκB, and significantly ameliorates lung fibrosis." (PMID 37569370, 2023). "Lung injury and pulmonary fibrosis increase airway elastance and in our study, both airway elastance and tissue elastance were increased in wild type mice treated with IL-1B." (PMID 38173934, 2023). "In addition, the same situations of inflammation, neutrophilia, and pulmonary fibrosis develop after IL-17A production following IL-1β treatment." (PMID 38202170, 2023). "Previous findings had reported that silica crystals induce the release of IL-1β and IL-18 and pulmonary interstitial fibrosis through the NLRP3 inflammasomes (tetracycline ameliorates silica-induced pulmonary inflammation and fibrosis via inhibition of caspase-1)." (PMID 36131930, 2022). "According to previous studies, IL1B could be a key pro-fibrotic mediator, and IL1B+FCN1hi cells were involved in skin and lung fibrosis, indicating that the cluster might be a new therapeutic target for SSc." (PMID 35185577, 2022). "In addition, IL-1β also stimulates the release of IL-6, which not only play the pro-inflammatory role, but also aggravates the pulmonary fibrosis by activating STAT3 pathway." (PMID 36733806, 2022). "Nintedanib blocks the polarization of both M1 and M2 human macrophages and markers that contribute to lung fibrosis (IL-1β, IL-8, IL-10, and CXCL13) by altering colony-stimulating factor 1 (CSF1) receptor (CSF1R) activation and its downstream PI3K/Akt signaling pathway." (PMID 36232756, 2022). "As the classic inflammatory cytokine, IL-1β plays an important role in pulmonary fibrosis." (PMID 36556326, 2022). "At the 24 h time‐point, terms associated with plasmin signaling, blood coagulation, NF‐kB, PDGF, TGF‐β, the Fra‐pathway implicated in pulmonary fibrosis as well as chemokine/inflammatory signaling, that is, S100A8‐complex or regulation of IL1β‐expression targets were identified." (PMID 34713625, 2021). "In terms of the toxicology mechanisms involved in rare earth pneumoconiosis, we have demonstrated a NLRP3 inflammasome pathway in macrophage-like cells responsible for REO-induced lung fibrosis by eliciting lysosomal damages, cathepsin B release, and IL-1β release." (PMID 33902647, 2021). "In addition, IL-1β leads to inflammation as well as stimulates the synthesis of collagen and fibrin by fibroblasts to promote pulmonary fibrosis." (PMID 34876129, 2021). "In lung tissue specimens, TNF-α and IL-1β were overexpressed in acute pulmonary fibrosis while presented a low expression level in old IPF patients, suggesting that TNF-α and IL-1β may be involved in the initiation of pulmonary fibrosis." (PMID 34393772, 2021). "Moreover, it has been described that IL6, TNF-α, and IL-1β lead to activation of the NF-kB pathway, which is the major controller of pulmonary fibrosis and epithelial–mesenchymal transition, in response to chronic inflammation." (PMID 32660140, 2020). "The activation of WNT/β-catenin in the development of pulmonary fibrosis may lead to the alveolar epithelium being a relevant source of IL-1β." (PMID 32694925, 2020). "However, the role of IL-1β remains controversial, since some work has shown that reduced inflammasome activation results in greater pulmonary fibrosis induced by ENMs." (PMID 33022979, 2020). "Importantly, macrophage derived IL-1β and inflammasome activation have been referred to as key features in various forms of lung fibrosis including IPF." (PMID 32431623, 2020).
pulmonary fibrosis (continued). "In particular, IL-1β plays a direct role in acute and chronic inflammation and pulmonary fibrosis." (PMID 32370250, 2020). "The secretome of senescent epithelial cells, including IL-1β, IL-6 and IL-8, promotes the differentiation of fibroblasts into myofibroblasts and their resistance to apoptosis, and thus leads to the progression of lung fibrosis." (PMID 33117807, 2020). "The results of the present investigation are in accordance with previous findings where instillation of BLM caused ROS influx which in turn phosphorylated IκBα and activated NF-κB resulting in the release of pro-inflammatory cytokines (TNF-α, IL-1β, and IL-6) and brought out pulmonary fibrosis." (PMID 31611754, 2019). "However, in contrast to these findings regarding IL‐1β in the skin, we observed that serum IL‐1β was positively correlated with KCO, and patients with high serum IL‐1β had higher DLCO and KCO, suggesting a reduced risk of lung fibrosis and PAH." (PMID 30997045, 2019). "Hesperidin alleviates BLM-induced IPF via inhibition of TGF-β1/Smad3/AMPK and IκBα/NF-κB pathways which in turn ameliorate the modulation of oxido-inflammatory markers (Nrf2 and HO-1) and pro-inflammatory markers (TNF-α, IL-1β, and IL-6) to reduce collagen deposition during pulmonary fibrosis." (PMID 31611754, 2019). "In pulmonary fibrosis, IL-1β is found to be upregulated, and the overexpression of IL-1β in rat lungs promotes the presence of myofibroblasts, fibroblast foci, and extracellular matrix accumulation which are the characteristics of pulmonary fibrosis." (PMID 31309122, 2019). "Besides, related researches have revealed that WNT/β-catenin signaling can induce IL-1β expression by alveolar epithelial cells in pulmonary fibrosis." (PMID 30147727, 2018). "To investigate whether ERCs play an anti-inflammatory role in the development and progression of pulmonary fibrosis, we have measured the content of IL-1β, TNF-α, and IL-10 in the serum and the lung tissue." (PMID 30147727, 2018). "Therefore, the NLRP3 inflammasome/IL-1β secretion axis is a promising therapeutic target for the prevention and treatment of lung fibrosis." (PMID 29084974, 2017). "Furthermore, our group has previously shown that prophylactic administration of BMMCs reduced mRNA levels of TGF-β, IL-1β, IL-1α, and IL-1RN and attenuated silica-induced lung fibrosis." (PMID 29126438, 2017). "Additionally, in idiopathic pulmonary fibrosis, the lung expresses high levels of IL-1β, IL-17A, and IL-23." (PMID 29254155, 2017). "To evaluate the anti-inflammatory and anti-fibrotic effects of CNP in BLM-induced lung fibrosis, we analyzed mRNA expression changes of pro-inflammatory cytokines (IL-1β and IL-6), pro-fibrotic cytokines and proteins (bFGF, TGF-β, TIMP1, and collagen 1A), and GC-B in the lungs." (PMID 26895702, 2016). "Given the clear importance of IL-1α, IL-1β and IL-33 in lung fibrosis and the likely compensatory action provided by members of the IL-1 cytokine family in vivo, targeting the shared receptors (for example, IL-1RAcP) may be more effective." (PMID 27001429, 2016). "Interleukin (IL)‐1β plays an important role in the pathogenesis of idiopathic pulmonary fibrosis." (PMID 27306439, 2016). "The importance of IL-1β/caspase-1 signaling has been shown in the BLM model of lung fibrosis." (PMID 27894300, 2016). "Based on our findings, 17(R)‐RvD1 attenuated the development of BLM‐induced pulmonary fibrosis in mice possibly through the downregulation of transcription of IL‐1β mRNA in mouse lung, and through the reduction in infiltration of neutrophils into bronchoalveolar tissues and BALF." (PMID 26660549, 2015). "Moreover, it has demonstrated to decrease IL-1β in bleomycin-induced pulmonary fibrosis in rats model." (PMID 23690844, 2013). "Increased levels of IL-1β in ARDS patients correlate with development of pulmonary fibrosis." (PMID 24406030, 2013). "In animal models of IPF, IL-1β levels are elevated in mice with bleomycin-induced lung fibrosis." (PMID 22322675, 2012).
pulmonary fibrosis (continued). "The IL-1β level in Treg-depleted group decreased significantly compared with that in silica-treated group, which suggested that Tregs depletion reduced IL-1β secretion in experimental model of silica-induced lung fibrosis." (PMID 22615967, 2012). "The higher IL-1β mRNA expression and protein level in silica-treated group might induce the Th17 inflammation in silica-induced lung fibrosis." (PMID 22615967, 2012). "Considering the increased number of macrophages in silica-treated group, we have a reason to believe that it might contribute to the Th17 differentiation in a silica-macrophages-IL-1β-Th17 way in experimental model of silica-induced lung fibrosis." (PMID 22615967, 2012). "Another study described how IL-17A may regulate the expression and/or proinflammatory properties of IL-22 in pulmonary fibrosis but did bot analysed the link between IL-1β, IL-23and IL-17." (PMID 21858022, 2011). "Importantly, TNF-α and IL-1β are key cytokines that mediate injury inflammation and the subsequent fibrosis in experimental lung fibrosis triggered by bleomycin." (PMID 20657842, 2010). "Mechanistically, UA-mediated NLRP3 inflammasome activation induces IL-1β overproduction, perpetuating pulmonary inflammation through fibroblast-to-myofibroblast transition and extracellular matrix deposition—a pathway corroborated in murine models of silica-induced lung fibrosis." (PMID 40837562, 2025). "Interestingly, previous studies show that the intranasal instillation of IL-1β induces pulmonary fibrosis and the EMT of alveolar epithelial cells, which might be associated with the activation of PI3K/AKT pathway." (PMID 39118068, 2024). "Therefore, we hypothesized that tetracycline reduces silica-induced lung injury and lung fibrosis resulting from chronic silicosis via limiting IL-1β and IL-18 driven inflammation." (PMID 35130879, 2022). "Moreover, monotherapy by L. minor protect the connective tissue deposition in the lungs which is evident from the statistically insignificantly decreased or commensurate to the control levels of the lung fibrosis-related IL-1β, IL-6, and TNF-α concentration, respectively." (PMID 35326173, 2022). "Also, it has been described that WNT/β-catenin signaling induces IL-1β expression by alveolar epithelial cells in a murine model of pulmonary fibrosis and an up-regulation of IL-1β in bronchoalveolar lavage fluid (BALF) in bleomycin-induced lung fibrosis in vivo." (PMID 33330522, 2020). "Nevertheless, the scutellarin treatment dose-dependently reduced the production of inflammatory cytokines IL-1β and IL-18, suggesting that the scutellarin could deliver anti-inflammatory function in pulmonary fibrosis in vitro and NF-κB/NLRP3 pathway might participate in this regulation process." (PMID 33188176, 2020). "IL-1β, which is associated with PAH, may also contribute to the pathogenesis of pulmonary fibrosis." (PMID 29861433, 2018). "Our study suggested that Tregs could promote Th17 cells differentiation by regulating TGF-β1 and IL-1β in silica induced lung fibrosis of mice, which further the understanding of the progress of silicosis and provide a new insight in the regulatory mechanism of Th17 by Tregs in lung inflammation." (PMID 22615967, 2012). "Therefore Tregs might promote Th17 response by modulating the macrophages-IL-1β-Th17 pathway in silica induced lung fibrosis." (PMID 22615967, 2012). "Critically, our study extends this paradigm to pulmonary fibrosis: FSTL1 overexpression in A549 cells amplified NF-κB and cytokines (IL-1β/TNF-α/IL-6), FSTL1 inhibition attenuated TGF-β1-induced inflammation." (PMID 40808692, 2025). "The levels of TNF-α, IL-1β, and IL-6 expression were enhanced in PM10-induced pulmonary fibrosis (p < 0.05)." (PMID 40299673, 2025). "Several recent publications have shown grounds for promise in identifying additional blood and tissue biomarkers, such as IL-1β, CXCL10, Eotaxin-3, PARC and IgE, in both COPD and pulmonary fibrosis." (PMID 41157273, 2025).
pulmonary fibrosis (continued). "Inflammatory cytokines, including TNF-α, IL-1β, IL-6, and TGF-β1, are recognized to play a role in the initiation and progression of pulmonary fibrosis." (PMID 40665395, 2025). "“Cytokine storm” is a typical feature of idiopathic pulmonary fibrosis (IPF), with IL-1β being a key pro-inflammatory cytokine in the development." (PMID 40423296, 2025). "MiRNA-21a-5p overexpression promoted lung fibrosis in bleomycin-induced SSc mice, inducing infiltration of cells expressing TNF-α, IL-1β, IL-6, or IL-17, along with STAT3 phosphorylated cells in the lesional skin." (PMID 38561750, 2024). "These lipid-lowering agents attenuated airway hyperresponsiveness, macrophages in BALF, lung fibrosis, serum leptin, free fatty acids, TGF-β1, IL-1β, IL-6, and IL-17a in the lung." (PMID 38762465, 2024). "As reported, inhibition of certain signaling pathways can ameliorate bleomycin-induced pulmonary fibrosis, such as NF-κB/NLRP3 signaling-mediated inflammation, the IL-1β/IL-1R1/MyD88/NF-κB axis, and IL-6/STAT3 pathway." (PMID 38913698, 2024). "In vivo, increased WNT/β-catenin signaling leads to the expression of the pro-inflammatory cytokines IL-1β and IL-6 in alveolar epithelial type cells in the bleomycin model, and it provides a WNT/interleukin axis link in the development of pulmonary fibrosis." (PMID 39596365, 2024). "iPSCs also, can downregulate the pro-fibrotic growth factors IGF-1,2, and repress several inflammatory mediators during pulmonary fibrosis, including TNF-α, IL-1β, IL-6, inducible nitric oxide synthase (iNOS) and nitric oxide (NO), but also PGE2." (PMID 38886859, 2024). "To characterize the kinetic effects of 2 U/kg i.t. bleomycin on various biochemical markers of lung fibrosis, we measured the concentrations of TGFβ1, IL6, TNFα, IL1β, CINC1, WISP1, VEGF, and TIMP1 in BALF at days 3, 7, and 14 following instillation." (PMID 38534359, 2024). "Overproduction of inflammatory mediators and cytokines such as inflammasome complexes, IL‐6, IL‐1β, TNF‐α, and the like leads to lung fibrosis in affected patients." (PMID 37773712, 2023). "Our study confirmed that the activation and accumulation of fibroblasts by NLRP3/IL-1β signaling significantly induced EMT, a key factor in pulmonary fibrosis." (PMID 38003456, 2023). "Increasing evidence has shown that IL-1β, IL-6, and TNF-α contribute to the pathogenesis of pulmonary fibrosis." (PMID 36830999, 2023). "Consequently, it is not surprising that the depletion of alveolar macrophages decreased the effects of IL-17 on the activation of lung fibrosis, supporting the hypothesis that these cells are involved first in the activation, producing pro-fibrotic factors such as IL-1β and IL-23." (PMID 38202170, 2023). "The transgenic mouse model was established for modeling pulmonary fibrosis by intratracheal delivered with adenovirus vector, followed by overexpressing of TGFα, TNF-α, TGF-β, IL-13 or IL-1β." (PMID 38007420, 2023). "Overproduction of inflammatory mediators and cytokines, such as inflammasome complexes, IL‐6, IL‐1β, and TNF‐α, can also lead to lung fibrosis in affected patients." (PMID 37773712, 2023). "SS-31 treatment significantly attenuated pulmonary fibrosis and inflammation induced by BLM, with reduced expression of IL-1β and IL-18." (PMID 38136142, 2023). "IL-1β is a classical downstream effector molecule of NLRP3, and previous studies have demonstrated the role of IL-1β in pulmonary fibrosis." (PMID 36694200, 2023). "It was observed that when CCL6 was neutralized in BLM-induced lung fibrosis, the expression levels of CCL3, CXCL1, CXCL2 and IL-1β were significantly reduced, indicating the effects of CCL6 on these chemokines and cytokine (sFigure 6B)." (PMID 36934284, 2023). "IL-1β and TNF-α work synergistically to increase the number of myofibroblasts, thereby promoting pulmonary fibrosis progression." (PMID 37214554, 2023).